ZFP57 (ZFP57 zinc finger protein)
Description:
Transcription regulator required to maintain maternal and paternal gene imprinting, a process by which gene expression is restricted in a parent of origin-specific manner by epigenetic modification of genomic DNA and chromatin, including DNA methylation. Acts by controlling DNA methylation during the earliest multicellular stages of development at multiple imprinting control regions (ICRs). Acts together with ZNF445, but ZNF445 seems to be the major factor in human early embryonic imprinting maintenance. In contrast, in mice, ZFP57 plays the predominant role in imprinting maintenance. Required for the establishment of maternal methylation imprints at SNRPN locus. Acts as a transcriptional repressor in Schwann cells. Binds to a 5'-TGCCGC-3' consensus sequence and recognizes the methylated CpG within this element (By similarity).
Synonyms: C6orf40; ZNF698; bA145L22; bA145L22.2; TNDM1
Tractability: PROTAC: ubiquitination databases record sites on it; its protein half-life has been measured.
Gene: Protein-coding gene on chromosome 6 (29,672,483 to 29,681,155, reverse strand). Ensembl gene ENSG00000204644.
Subcellular location: Nucleus
Gene Ontology:
Molecular function: chromatin binding; protein binding; DNA-binding transcription factor activity, RNA polymerase II-specific; RNA polymerase II transcription regulatory region sequence-specific DNA binding
Biological process: autosome genomic imprinting; regulation of transcription by RNA polymerase II; regulation of DNA-templated transcription
Cellular component: nucleus
Genetic constraint (gnomAD): Loss-of-function variants: 12 observed, 17.15 expected, observed/expected ratio (o/e) 0.7, 90% interval 0.45 to 1.13. The synonymous counts are far from expectation, so gnomAD's model fits this gene poorly and the ratio says little. Missense variants: 536 observed, 689.15 expected, observed/expected ratio (o/e) 0.78, 90% interval 0.72 to 0.83. Synonymous variants: 203 observed, 256.93 expected, observed/expected ratio (o/e) 0.79, 90% interval 0.7 to 0.89.
Homologues: Orthologues: chimpanzee ZFP57 (99% identical), macaque ZFP57 (94% identical), rabbit ZFP57 (61% identical), pig ZFP57 (56% identical), mouse Zfp57 (32% identical), rat Zfp57 (29% identical). Paralogues in human: ZNF707 (22% identical), ZNF287 (21% identical), ZNF34 (21% identical), ZKSCAN7 (20% identical), ZNF527 (20% identical), ZNF333 (20% identical), ZNF17 (20% identical), ZNF416 (20% identical), ZNF285 (19% identical), ZNF777 (19% identical), ZNF407 (19% identical), ZNF776 (19% identical), and 38 more.
Diseases named in the same sentence as ZFP57 in open-access papers:
ZFP57 is named in the same sentence as 64 diseases in open-access papers, as found by Europe PMC text mining. Sharing a sentence is not in itself a finding about the gene and the disease. The quoted sentences say what the papers report.
transient neonatal diabetes mellitus (11 papers, 2009 to 2024). Transient neonatal diabetes mellitus (TNDM) is a genetically heterogeneous form of neonatal diabetes (NDM) characterized by hyperglycemia presenting in the neonatal period that remits during infancy but recurs in later life in most patients. "Approximately half of transient neonatal diabetes mellitus (TNDM) patients with methylation disturbance at PLAGL1 have biallelic pathogenic variants in ZFP57, and have MLID involving LOM at PLAGL1, GRB10, and PEG3." (PMID 39090763, 2024). "The zinc finger protein 57 homolog (ZFP57) gene, a transcriptional repressor, is involved in genomic imprinting and mutations in this gene have been associated with transient neonatal diabetes mellitus." (PMID 37606455, 2023). "Moreover, the structure of the DNA binding motif of ZFP57 has been determined and mutations of ZFP57 associated to Transient neonatal diabetes mellitus 1 (TNDM1) have been demonstrated to affect DNA binding activity." (PMID 24294107, 2013). "A further possible criticism in our hypothesis concerns the normal methylation of the H19/IGF2:IG-DMR in transient neonatal diabetes mellitus 1 (TNDM1, OMIM 601410) patients with loss of function mutations of ZFP57 and multi-locus imprinting disturbances (MLID)." (PMID 29484033, 2018). "The imprinting disorder ‘transient neonatal diabetes mellitus’ (TNDM, OMIM 601410) is caused by mutations in the human ZFP57 gene and presents a relatively minor clinical phenotype." (PMID 31810366, 2019). "Thus individuals homozygous for ZFP57 mutations presented with transient neonatal diabetes mellitus (TNDM)." (PMID 19300480, 2009).
breast carcinoma (7 papers, 2019 to 2024). "One study showed that ZFP57 was downregulated in breast cancer, while ZFP57 overexpression inhibited breast cancer cell proliferation by inhibiting the Wnt/β-catenin pathway." (PMID 36276285, 2022). "On the other hand, ZFP57 was recently reported to suppress the proliferation of breast cancer cells through downregulation of the Wnt/β-catenin signaling pathway." (PMID 34638319, 2021). "ZFP57 expression levels in 80 paired human breast cancer specimens and adjacent normal tissues were analysed using mRNA qRT-PCR." (PMID 30787268, 2019). "In this study, we investigated the expression levels of ZFP57 and its biological functions in breast cancer." (PMID 30787268, 2019). "The ZFP57 expression in breast cancer tissues was of a lower level than that in adjacent normal tissues." (PMID 30787268, 2019). "Taken together, these findings supported the notion that ZFP57 is involved in the growth of breast cancer cells." (PMID 30787268, 2019). "In this study, we primarily confirmed that the expression level of ZFP57 was down-regulated in both breast cancer tissue samples and cell lines compared to adjacent normal tissues and nontumorigenic HBL-100 cells, which is consistent with the TCGA database." (PMID 30787268, 2019). "Overexpression of ZFP57 inhibited growth of breast cancer cells both in vitro and in vivo significantly." (PMID 30787268, 2019). "In summary, our study demonstrates that the ES-specific transcription factor ZFP57 is a tumour suppressor factor in breast cancer and targets oncogenic MEST directly through regulating the methylation of the MEST promoter region and subsequently suppressing the Wnt/β-catenin pathway." (PMID 30787268, 2019). "The data showed that ZFP57 was obviously decreased in breast cancer tissues." (PMID 30787268, 2019). "Zinc finger protein 57 (ZFP57), a member of KRAB-ZFPs, could maintain DNA methylation in embryonic stem cells (ESCs), although its role and underlying mechanisms in breast cancer are not well understood." (PMID 30787268, 2019). "ZFP57 expression was lower in the breast cancer cell lines than it was in HBL-100 cells." (PMID 30787268, 2019). "In this study, we found that ZFP57 had low expression in breast cancer, and overexpression of ZFP57 could inhibit the proliferation of breast cancer cells by inhibiting the Wnt/β-catenin pathway." (PMID 30787268, 2019). "Since it has been indicated that several KRAB-ZFPs could act as tumour suppressors in multiple types of tumours, such as breast cancer, the expression pattern and biological functions of ZFP57 in breast cancer remain to be elucidated." (PMID 30787268, 2019). "The data indicated that the aberrant expression level of ZFP57 not only correlated with breast cancer development, but could also regulate proliferation activity of breast cancer cells." (PMID 30787268, 2019). "To verify our hypothesis that ZFP57 can participate in tumorigenesis through regulating DNA methylation of TSGs or oncogenes in breast cancer, we further explored the mechanism of ZFP57 on tumour suppression of breast cancer." (PMID 30787268, 2019). "Moreover, analysis of MS-PCR appeared to show that the promoter region of the MEST was significantly hypomethylated in breast cancer tissues as opposed to normal adjacent tissues or, rather, MEST expression was regulated by ZFP57 through conserving its DNA methylation in breast cancer cells." (PMID 30787268, 2019). "Taken together, they illustrated that MEST may be the functional target of ZFP57 in breast cancer." (PMID 30787268, 2019). "However, little is known about the expression and function of ZFP57 in breast cancer." (PMID 30787268, 2019). "ZFP57-MEST and the Wnt/β-catenin pathway axis are involved in breast tumorigenesis, which may represent a potential diagnostic biomarker, and provide a new insight into a novel therapeutic strategy for breast cancer patients." (PMID 30787268, 2019).
breast carcinoma (continued). "The good correlation between ZFP57 and MEST expression in tissues led us to further explore the possibility that ZFP57 regulates MEST expression in breast cancer cells." (PMID 30787268, 2019). "Besides this, the results suggested that elevated or reduced expression of ZFP57 can decrease or increase expression of MEST, respectively in breast cancer cells." (PMID 30787268, 2019). "Further, mRNA qRT-PCR and Western blot were performed to examine ZFP57 expression in non-tumourigenic HBL-100 cells and breast cancer cell lines (MCF-7, ZR-75-1, T47D, MDA-MB-231 and SUM1315)." (PMID 30787268, 2019).
diabetes (4 papers, 2014 to 2023). "The ZFP57 genes was one of 38 genes potentially associated with monogenic diabetes in a next-generation sequencing study." (PMID 37606455, 2023). "Interestingly, two different variants in the same gene (called ZFP57 - Zinc finger protein 57) were associated with diabetes in two different breeds." (PMID 26401325, 2014). "FGFR2 associated with obesity and weight at birth and with adult obesity; DUSP22 related to diabetes and obesity, and ZFP57 related to nutrition/neonatal diabetes." (PMID 36091392, 2022).
glioma (4 papers, 2021 to 2026). A benign or malignant brain and spinal cord tumor that arises from glial cells (astrocytes, oligodendrocytes, ependymal cells). "ZFP57 expression was upregulated in high-grade gliomas compared to low-grade gliomas, as well as in breast, esophageal, gastric, and colon cancers." (PMID 33672287, 2021). "Furthermore, specific mutations in HUSE.017 and HUSE.050 increased the predicted binding of ZFP57 and zinc finger and BTB domain-containing 12 (ZBTB12), two TFs linked to chromatin remodeling and transcriptional repression in gliomas." (PMID 41019514, 2026). "Briefly, ZFP57—the embryonic stem cell-specific transcription factor—is involved in colorectal cancer spreading, and its overexpression was observed in high-grade gliomas, suggesting the oncogenic role in tumorigenesis." (PMID 34638319, 2021). "Finally, the SNV affecting EE-021 (chr12:3227012C>G) substantially increased the binding affinity of zinc finger protein 57 (ZFP57) and CCCTC-binding factor-like (CTCFL), both related to glioma progression and epigenetic regulation." (PMID 41019514, 2026).
hydatidiform mole (4 papers, 2009 to 2022). A gestational trophoblastic disorder characterized by marked enlargement of the chorionic villi, hyperplasia of the villous trophoblastic cells and hydropic changes. "In this sense, mutations in some genes lead to multilocus loss of methylation: ZFP57 in TNDM patients, NALP7 and C6orf221 in familial biparental hydatidiform mole, or NLRP2 in a family with BWS." (PMID 26106604, 2015). "Pathological variants of zinc finger protein genes such as ZFP57 and ZNF445 and of genes related to the subcortical maternal complex such as NLRP2, NLRP5, NLRP7, and KHDC3L have been identified in cases of multilocus imprinting disturbances (MLIDs) and recurrent hydatidiform moles (RHMs)." (PMID 35581658, 2022). "This epigenetic heterogeneity contrasts with the relatively consistent MLID characteristic of recessive ZFP57 mutation, or the complete loss of maternal methylation seen in hydatidiform moles, and suggests that these variants affect not gametic establishment but postzygotic maintenance of imprints." (PMID 29574422, 2018).
autism (3 papers, 2022 to 2023). Persistent deficits in social interaction and communication and interaction as well as a markedly restricted repertoire of activity and interest as well as repetitive patterns of behavior. "Lastly ZFP57 has been associated with general cognitive ability, schizophrenia, autism, and rheumatoid arthritis." (PMID 37258616, 2023). "DUSP22 was also related to schizophrenia, ZFP57 with autism, and FGFR2 with depression." (PMID 36091392, 2022).
colorectal cancer (3 papers, 2018 to 2023). A primary or metastatic malignant neoplasm that affects the colon or rectum. "Our finding that elevated methylation at ZFP57 is associated with a reduced risk of later colorectal cancer is consistent with data suggesting ZFP57 is an oncogene." (PMID 29310692, 2018). "In the clinical samples, high levels of ZFP57 were shown to be positively associated with NANOG expression, as well as nodal and liver metastasis in colorectal cancer." (PMID 37492743, 2023). "Furthermore, ZFP57 overexpression resulted in higher metastatic potential in the mouse model of colorectal cancer, as reported by Shoji and colleagues." (PMID 37492743, 2023).
lung carcinoma (3 papers, 2019 to 2023). "It has recently been hypothesized that ZFP57 is a potential susceptibility gene for lung cancer development through the increase of IGF2 expression." (PMID 34262872, 2021). "Moreover, a recent GWAS revealed that ZFP57 is a potential disease susceptibility gene for lung cancer development." (PMID 31245293, 2019). "Since ZFP57 regulates IGF2 expression, this axis may well be a potential target for lung cancer treatment." (PMID 31245293, 2019).
neonatal diabetes mellitus (3 papers, 2009 to 2021). Neonatal diabetes mellitus presents as hyperglycemia, failure to thrive and, in some cases, dehydration and ketoacidosis which may be severe with coma, in a child within the first months of life. "Zfp57-knockout mice display broad alterations of genomic imprints, while mutations in human Zfp57 correlate with transient neonatal diabetes mellitus, a disease associated with imprinting defects." (PMID 23451074, 2013).
schizophrenia (3 papers, 2022 to 2024). A major psychotic disorder characterized by abnormalities in the perception or expression of reality. "For example, ZFP57 is associated with autism spectrum disorder and PTSD symptoms, while POLD4 is linked to schizophrenia." (PMID 39020437, 2024).
AIDS (2 papers, 2015 to 2022). A syndrome resulting from the acquired deficiency of cellular immunity caused by the human immunodeficiency virus (HIV). "Expression of ZFP57 is dependent on underlying genetic variation, and while the biology of ZFP57 in adults is not well studied, it has been implicated as the causal gene connecting some GWAS variants to cancer and HIV/AIDS progression." (PMID 34919805, 2022).
ovarian carcinoma (2 papers, 2023 to 2024). A malignant neoplasm originating from the surface ovarian epithelium. "In summary, highly expressed of ZFP57 in ovarian cancer was significantly correlated with advanced SOC and high-grade OC, and also indicated poor prognosis of OC patients." (PMID 37497403, 2023). "The clinical pathological analysis in the table shows that the high expression of ZFP57 in ovarian cancer is related to benign and malignant, clinical staging, pathological grading of OC patients." (PMID 37497403, 2023). "Then we analyzed 3 independent ovarian cancer microarray data (GSE14407, GSE18520, GSE40596) in the GEO database and found that ZFP57 mRNA expression was also increased significantly in OC tissues compared with normal ovarian surface epithelium tissues (all P values were less than 0.05)." (PMID 37497403, 2023).
pancreatic cancer (2 papers, 2022 to 2025). "In our study, ZFP57 was downregulated in pancreatic cancer after radiotherapy and the Wnt/β-catenin pathway was activated, thereby enhancing the radioresistance of pancreatic cancer cells." (PMID 36276285, 2022). "Our experiments showed that the miR-193a-5p/ZFP57/Wnt pathway mediated the radioresistance of pancreatic cancer cells, providing novel clues for the treatment of pancreatic cancer." (PMID 36276285, 2022). "This study was to investigate whether miR-193a-5p and ZFP57 are involved in the radioresistance of pancreatic cancer and to explore its working mechanism." (PMID 36276285, 2022). "The results above suggested that the ZFP57 expression might be related to the radioresistance of pancreatic cancer." (PMID 36276285, 2022). "ZFP57 was downregulated in radioresistant pancreatic cancer cells." (PMID 36276285, 2022). "It was demonstrated that miR-193a-5p targets ZFP57, suppressing its expression and upregulating cyclin 1, CDK4, and Bcl-2 to activate the Wnt/β-catenin pathway, enhancing radioresistance in pancreatic cancer cell tumors." (PMID 40161373, 2025). "Hence, the ZFP57 expression might be related to the prognosis of pancreatic cancer." (PMID 36276285, 2022).
post-traumatic stress disorder (2 papers, 2021 to 2022). An anxiety disorder precipitated by an experience of intense fear or horror while exposed to a traumatic (especially life-threatening) event. "Zinc finger protein 57 (ZFP57) has not been previously linked to a neurodegenerative disorder, but its involvement in neurological health is evidenced by research in post-traumatic stress disorder (PTSD)." (PMID 33981329, 2021).
psychosis (2 papers, 2017 to 2025). "Overall, our results suggest that in exposed individuals, ZFP57 methylation may be associated with psychosis." (PMID 28406917, 2017). "Compared to exposed individuals without psychosis, exposed individuals with psychosis had differential methylation in the region encompassing the gene encoding the zinc finger protein 57 (ZFP57)." (PMID 28406917, 2017). "The authors found hypermethylation at differentially methylated regions in the ZFP57 gene and the promoter of the ADAM TS9 gene in the group of DES/EE-exposed children with psychosis compared with those without psychosis." (PMID 41149748, 2025).
Alzheimer disease (1 paper, 2024). A progressive, neurodegenerative disease characterized by loss of function and death of nerve cells in several areas of the brain leading to loss of cognitive function such as memory and language. "We also observed 3 additional DMRs annotated to ZFP57, ALLC, ABI3, and all of them have been described to be involved in Alzheimer’s disease (AD)." (PMID 38845005, 2024).
asthma (1 paper, 2020). "For example, whole blood QTLs related to genes known to affect asthma pathogenesis or severity (e.g. IL18R, ZFP57, BTN3A2, NDFIP1, SMAD3, CLEC16A, and TSLP) were associated with colocalization sites for asthma and neutrophil, eosinophil, monocyte and/or lymphocyte traits." (PMID 32600345, 2020).
autoimmune disease (1 paper, 2019). A disorder resulting from loss of function or tissue destruction of an organ or multiple organs, arising from humoral or cellular immune responses of the individual to their own tissue constituents. "Recently, ZFP57 has been identified as a candidate gene contributing to HLA associated diseases including cancers, autoimmune diseases, and HIV." (PMID 31296227, 2019).
congenital heart disease (1 paper, 2024). A heart disease that is present at birth. "The ZFP57 gene mutation causes another type of TNDM that is also associated with congenital heart disease, such as persistent foramen ovale." (PMID 38998792, 2024).
embryonic carcinoma (1 paper, 2022). "Transcription factor ZFP57 was first identified as an undifferentiated cell-specific gene in F9 embryonic carcinoma cells." (PMID 36276285, 2022).
Fabry disease (1 paper, 2025). Fabry disease (FD) is a progressive, inherited, multisystemic lysosomal storage disease characterized by specific neurological, cutaneous, renal, cardiovascular, cochleo-vestibular and cerebrovascular manifestations. "This study showed that certain genes were hypermethylated in males with Fabry disease, particularly the zinc finger protein gene (ZFP57), which plays a role in methylation at imprinting regions." (PMID 41150803, 2025).
glioblastoma (1 paper, 2017). The most malignant astrocytic tumor (WHO grade IV). "High grade glioblastoma has also been associated with aberrant ZFP57 expression." (PMID 28406917, 2017).